HIPK3 (homeodomain interacting protein kinase 3)
Diseases named in the same sentence as HIPK3 in open-access papers (continued):
Sharing a sentence is not in itself a finding about the gene and the disease.
non-small cell lung carcinoma (3 papers, 2021 to 2025). A group of at least three distinct histological types of lung cancer, including non-small cell squamous cell carcinoma, adenocarcinoma, and large cell carcinoma. "A study found that the expression levels of HIPK3 mRNA and protein were significantly down-regulated in human non-small cell lung cancer (NSCLC) tissues, and HIPK3 silencing promoted the invasion and metastasis of NSCLC." (PMID 36703984, 2022). "It has been reported that HIPK3 can be a valuable biomarker for the survival prognosis of patients with non-small cell lung cancer." (PMID 33495417, 2021). "Additionally, HIPK3 expression serves as a valuable biomarker for survival and prognosis in non-small cell lung cancer, and low HIPK3 expression correlates with poor prognosis in renal cell carcinoma." (PMID 40280416, 2025). "Thus, HIPK3 may be a valuable biomarker for predicting the prognosis of patients with non-small cell lung cancer." (PMID 36703984, 2022).
pancreatic cancer (3 papers, 2016 to 2021). "Analogously, circ-HIPK3 improved the gemcitabine resistance through promoting cell viability and metastasis in pancreatic cancer cells." (PMID 34295807, 2021). "HIPK3 has been related to apoptosis resistance, CBR1 has been identified as a patient survival marker, ALDH3A1 and ALDH3A2 have been related to drug response, and NOS1 has been related to pancreatic cancer risk." (PMID 29285214, 2017).
cardiac hypertrophy (2 papers, 2022 to 2023). "A study by Xu and colleagues demonstrated that circHIPK3, a circular RNA produced by the third exon of the Homeodomain Interacting Protein Kinase 3 (HIPK3) gene, sponges miR-185-3p in cardiac hypertrophy." (PMID 35681500, 2022).
clear cell renal cell carcinoma (2 papers, 2021 to 2023). "Among the 4 HIPKs, HIPK1 and HIPK3 mRNA expression was downregulated in cancer tissues from The Cancer Genome Atlas Kidney Clear Cell Carcinoma (TCGA-KIRC) database." (PMID 33495417, 2021).
leukemia (2 papers, 2011 to 2019). A malignant (clonal) hematologic disorder, involving hematopoietic stem cells and characterized by the presence of primitive or atypical myeloid or lymphoid cells in the bone marrow and the blood. "We also found that BS008 exerts an effect on AS of these gene transcripts in K562 leukemia cells by detecting an increase in the proapoptotic splice variants BCL‐XS, SMAC‐3, and HIPK3 U(−) with a concomitant decrease in the antiapoptotic splice variant HIPK3 U(+)." (PMID 31152681, 2019).
liver cancer (2 papers, 2018 to 2019). An epithelial or non-epithelial malignant neoplasm that arises from the liver. "Recent study shows that circHIPK3, circRNA derived from the HIPK3 gene Exon2, was found to be significantly abundant in various tissues compared with HIPK3 and upregulated in liver cancer compared with matched normal tissues." (PMID 28840253, 2018).
Myocardial fibrosis (2 papers, 2023 to 2025). "Since a circRNA from Hipk3 has been reported to aggravate myocardial fibrosis, we wondered if such circRNAs exerted pro-hypertrophic effects." (PMID 36800233, 2023). "Circ_0001052 is sourced from Hipk3 (homeodomain-interacting protein kinase 3) and is reported to aggravate myocardial fibrosis." (PMID 36800233, 2023). "Also, circRNA from Hipk3 (circ-Hipk3) was suggested to aggravate myocardial fibrosis via sponging miR-29b-3p." (PMID 36800233, 2023).
acute myeloid leukemia (1 paper, 2023). Acute myeloid leukemia (AML) is a group of neoplasms arising from precursor cells committed to the myeloid cell-line differentiation. "In this study, we identified SE-associated genes by integrating cell-specific SEs with RNA-seq data and found six genes (CAPG, CD207, GPR132, SLC7A11, HIPK3 and FCER1G) that are correlated with poor prognosis in acute myeloid leukemia (AML) patients according to the TCGA-LAML database." (PMID 37296281, 2023).
breast tumors (1 paper, 2010). "However, several putative SRC substrates, including HIPK3, STAT5A, p120, FRK and Hrs, were frequently phosphorylated in multiple breast tumors." (PMID 21049007, 2010). "Analysis of the overlap between substrates phosphorylated in our study and in human tumors defined a group of proteins that may be most relevant to Src activity in human cancers: HIPK3, STAT5A, p120, Hrs and FRK in human breast tumors, and p130Cas, p120, FRK, Hrs and KIAA0323 in human lung tumors." (PMID 21049007, 2010).
cerebrovascular diseases (1 paper, 2021). "At the same time, hsa_circ_0001946 (circ-CDR1as) and hsa_circ_0000284 (circ-HIPK3) were selected by reviewing the literature, they are two circRNAs closely related to cerebrovascular diseases that are currently being noticed." (PMID 33746870, 2021).
diabetes (1 paper, 2022). "Mmu_circ_0001052 is a homolog of circRNA HIPK3 in mice which is considered as the role functioning cardiovascular disease and diabetes." (PMID 35870977, 2022).
gallbladder cancer (1 paper, 2021). "Such as, circular RNA HIPK3 was high expression and promoted gallbladder cancer cell growth by sponging microRNA-124." (PMID 34489401, 2021).
HCMV infection (1 paper, 2022). "Interestingly, the results of both RT-PCR and ampFISH showed that the expression of circHIPK3 is upregulated by HCMV infection and that RNAs R treatment leads to loss of linear RNA but not circular HIPK3 RNA." (PMID 35604147, 2022).
Hyperglycemia (1 paper, 2020). An increased concentration of glucose in the blood. "For example, circulating RNA HIPK3 (homeodomain-interacting protein kinase 3) can bind miR-192-5p with upregulation of transcription factor FOXO1 (forkhead box protein O1) leading to hyperglycemia and insulin resistance." (PMID 32993185, 2020).
lymph-node metastasis (1 paper, 2023). "Significantly associated with longer survival time were being male, lacking lymph-node metastasis, having papillary tumor type and, in particular, high HIPK3 levels." (PMID 38105269, 2023).
oral squamous cell carcinoma (1 paper, 2021). "Circ-HIPK3 provides a new approach for the diagnosis and treatment of oral squamous cell carcinoma through miR-381-3p/YAP1." (PMID 34905439, 2021).
renal carcinoma (1 paper, 2021). A carcinoma arising from the epithelium of the renal parenchyma or the renal pelvis. "Further validation of HIPK3 with Gene Expression Omnibus (GEO66727, GEO53757) showed that the downregulation of HIPK3 in renal cancer." (PMID 33495417, 2021). "According to the analysis of CCK8 test results, HIPK3 overexpression can inhibit the proliferation function of renal cancer cells." (PMID 33495417, 2021). "High expression of HIPK3 is correlate with good OS and DFS of renal cancer between wild-type and mutation subsets of these genes." (PMID 33495417, 2021). "To investigate the possible role of HIPK3 in renal cancer cells, we transfected HIPK3 overexpression (OE-HIPK3) and OE-NC plasmids into 786-O and A498 cells to test the effect of HIPK3 on cancer cell growth in vitro." (PMID 33495417, 2021). "Immunohistochemistry (IHC) results also showed that HIPK3 was downregulated in renal cancer tissues." (PMID 33495417, 2021). "Western blotting of 12 paired ccRCC tissues showed that the protein of HIPK3 was downregulated in renal cancer." (PMID 33495417, 2021). "We then confirmed that HIPK3 expression in ccRCC tissues was lower than that in normal kidney tissues, and overexpression of HIPK3 could inhibit the proliferation, migration, and invasion of renal cancer cells." (PMID 33495417, 2021). "Our research results showed HIPK3 had a significantly lower expression in renal cancer tissues, and its low expression predicted a poor prognosis, and univariate analysis and multivariate analysis also indicates that low expression may be a novel independent prognostic marker for ccRCC." (PMID 33495417, 2021).
renal cell carcinoma (1 paper, 2025). "Growing evidence suggests that HIPK3 functions as a tumor suppressor in several cancers, including lung, gastric, hepatocellular, and renal cell carcinomas." (PMID 40280416, 2025).
rheumatoid arthritis (1 paper, 2022). A chronic, systemic autoimmune disorder characterized by inflammation in the synovial membranes and articular surfaces. "Over-expression of HIPK3 in immune cells in rheumatoid arthritis (RA) has been reported." (PMID 36703984, 2022).
T-cell leukemia (1 paper, 2020). A malignant disease of the T-lymphocytes in the bone marrow, thymus, and/or blood. "When overexpressed, these miRNAs act as oncogenes and are strongly implicated in T cell leukemia development by targeting myosin regulatory light chain-interacting protein (Mylip), retinoblastoma-binding protein 1-like (Rbp1-like), and homeodomain-interacting protein kinase 3 (Hipk3)." (PMID 32645881, 2020).
type 2 diabetes (1 paper, 2015). "Recently, HIPK3−/− mice were shown to have impaired glucose-induced insulin secretion, and HIPK3 has been implicated in the pathogenesis of human type 2 diabetes." (PMID 25630557, 2015).
WAGR syndrome (1 paper, 2008). WAGR syndrome (Wilms tumor - aniridia - genitourinary anomalies - intellectual disability mental retardation) is a rare genetic disorder characterized by an unusual complex of congenital developmental abnormalities with intellectual disability, and an increased risk of developing Wilms tumor. "Eight probes were screened in the 11p13 region associated with WAGR syndrome, in BDNF (2 probes), PAX6 (3 probes), WT1 (2 probes) and HIPK3 (1 probe)." (PMID 18925931, 2008).
cancer (35 papers, 2009 to 2025). A tumor composed of atypical neoplastic, often pleomorphic cells that invade other tissues. "However, the mechanisms underlying HIPK3 downregulation in various cancers remain poorly understood." (PMID 40280416, 2025). "HIPK3 is aberrantly expressed in malignant tumors and is associated with apoptosis." (PMID 37581369, 2023). "The third known Tra2β-target exon which might be potentially relevant in cancer cells is in the HIPK3 gene, which encodes a serine/threonine kinase involved in transcriptional regulation and negative control of apoptosis." (PMID 23935626, 2013). "Furthermore, HIPK3 downregulation is significantly associated with poor prognosis in other cancers." (PMID 40280416, 2025). "The WWP1/HIPK3 axis modulates cancer cell chemosensitivity through the regulation of the JNK signaling pathway." (PMID 40280416, 2025). "Studies have shown that HIPK3 possesses oncogenic features, while the derived circHIPK3 is downregulated in cancer and possesses tumor suppressor functions." (PMID 39041323, 2024). "CircHIPK3 is formed from the second exon of the HIPK3 gene and has been found in various pathologies, including different types of cancer." (PMID 38505596, 2024). "The downregulation of miR-124 by circ_HIPK3 can promote cancer cell survival and proliferation by inducing the overexpression of its target genes, such as SphK1, STAT3, and CDK4." (PMID 36769372, 2023). "Low HIPK3 expression was a poor prognostic factor and HIPK3 expression was significantly down-regulated in ccRCC cancer tissues when compared with normal renal tissues." (PMID 33495417, 2021). "Circ-HIPK3 plays an important role in cancers by sponging multiple miRNAs, thereby promoting miRNA-124 and circFoxo3-mediated inhibition of the growth and survival of cancer cells." (PMID 34368160, 2021). "Research indicates that circular RNA HIPK3 (circHIPK3) is crucial to cell autophagy and apoptosis in various cancer types." (PMID 33824287, 2021). "HIPK3, a FAS/FADD-interacting kinase downregulated in our study, has been previously implicated in multidrug resistance in cancer." (PMID 32260415, 2020). "Since we have previously reported that amiloride regulates the AS of BCL‐X and HIPK3 pre‐mRNA in various cancer cell lines including human HCC cell line Huh‐7, it would be of interest to investigate if BS008 had the same effects on AS in Huh‐7." (PMID 31152681, 2019). "These HIPK3 isoforms can be regulated by c-Jun NH2-terminal kinase in cancer cells, thus contributing to an increased resistance to Fas receptor-mediated apoptosis." (PMID 28779122, 2017). "Here, the authors identify thousands of circular RNAs differentially expressed between normal and cancer tissues and show that an abundant circular RNA generated from HIPK3 regulates cell growth." (PMID 27050392, 2016). "HIPK3 has been recognized as a tumor suppressor across various cancers." (PMID 40280416, 2025). "Increasing evidence suggests that HIPK3 acts as a tumor suppressor in various cancers." (PMID 40280416, 2025). "Similarly, circ_HIPK3 has been known as a crucial oncogenic regulator in several cancer pathologies by suppressing two miRNAs, miR-124 and miR-149." (PMID 36769372, 2023). "The depletion of circ-HIPK3 reduces cell proliferation, migration, invasion, and EMT of gemcitabine-resistant cells, implying that the circ-HIPK3/miR-330-5p/EMT axis may regulate the effect of other cancer therapies." (PMID 33799952, 2021). "Reportedly, the circRNA, circHIPK3, which was derived from Exon2 of HIPK3, contributes to cancer progression by adsorbing miR-124 in many types of cancer, including liver cancer, glioma, lung cancer, gastric cancer, gallbladder cancer, and oral squamous cell carcinoma." (PMID 34072894, 2021). "Circular RNA HIPK3 (circHIPK3) is a circular RNA (circRNA) related to cancer progression." (PMID 33005182, 2020).
cancer (continued). "According to the results of the analysis of malignant tumors, NCOA1, HERC1, HIPK3, MBNL1, hsa-let-7b-3p, hsa-miR-378a-5p, and hsa-miR-26a-5p were predictive or prognostic factors for malignant tumors." (PMID 33841514, 2021). "circHIPK3 expression has been investigated in several cancer cell lines, including CRC cells, showing higher levels compared to the linear HIPK3 transcripts." (PMID 30195762, 2018). "We discovered that 4bHWE decreases the proportion of HIPK3 U (+) and increases the proportion of SMAC-3 and SURVIVIN Delta Ex3 in human cancer cell lines." (PMID 28779122, 2017). "Another Fas/FADD-interacting kinase, HIPK3 (PKY), was first identified as a putative multidrug-resistant protein from studies of cancer cells." (PMID 19549311, 2009). "It appears that the interactomes of five out of the 17 lithium-sensitive genes (ADCY2, ADCY5, ADCY7, BPNT1, and HIPK3) do not show significant mutual enrichment with the cancer pathways explored in this study." (PMID 31114752, 2019).
tumor (23 papers, 2014 to 2025). "Clinically, this metabolic shift caused by HIPK3 overexpression weakens tumor and sensitizes it to chemotherapy." (PMID 35096570, 2021). "The results indicate that low expression of HIPK3 in ccRCC tissues is significantly associated with poor survival rates in tumor patients, and HIPK3 may be used as a valuable biomarker and inhibitor of ccRCC." (PMID 33495417, 2021). "Interestingly, low circ-HIPK3 expression was positively associated with tumour grade, invasion, and the lymph node metastasis, suggesting its potential clinical value as a novel biomarker for early diagnosis and targeted therapy." (PMID 31937318, 2020). "Hence, we sought to determine whether the anti-tumor phenotype associated with miR-382 overexpression could be rescued by KLF12 or HIPK3 overexpression in miR-382-overexpressing cells." (PMID 25344865, 2014). "In contrast, HIPK3 overexpression promoted tumor growth, and partially reversed the inhibitory effects of WWP1 knockdown on tumor growth." (PMID 40280416, 2025). "Both in vitro and in vivo experiments have indicated that the downregulation of HIPK3 exerts effects contrary to those of HIPK3 overexpression, notably leading to increased tumor proliferation and increased metastatic potential." (PMID 39335515, 2024). "These in vitro results were validated in a mouse model with a smaller tumor size and weight, documented after silencing circ-HIPK3." (PMID 36139487, 2022). "Circ-HIPK3 sponges miR-421, thus causing ZIC5 overexpression, which can drive tumor progression and drug resistance." (PMID 36139487, 2022). "According to our results, HIPK3, a potential tumor suppressor, is a target of and therefore repressible by 101-3p." (PMID 35096570, 2021). "Statistical analysis revealed that HIPK3 expression is lower in tumor samples with a p value less than 0.001, while that of 101-3p is higher in tumor samples with a p value once again less than 0.001." (PMID 35096570, 2021). "Stereotypic characterizations of HIPK3-overexpressing cell lines showed HIPK3 is likely a tumor suppressor and sensitizes CRC cell lines to 5-FU." (PMID 35096570, 2021). "In vitro experiments showed that overexpression of HIPK3 can inhibit tumor cell growth, invasion, and migration." (PMID 33495417, 2021). "Results in this section suggest overexpression of HIPK3 decreases oncogenicity of both HCT116 and SW480, and therefore implicate HIPK3’s positive contribution towards tumor suppression." (PMID 35096570, 2021). "Beside, the Xenograft model result parallel to the in vitro results, KLF12 overexpression stimulated tumor growth and HIPK3 overexpression induced chemoresistance in LS1034." (PMID 29700213, 2019). "Here, our data show that overexpression of miR-382-induced HIPK3 decreased, which impairs tumor cell survival and induces CDDP-resistant cells acquisition chemically sensitive again and vice versa." (PMID 29700213, 2019). "Then, overexpression of KLF12 and HIPK3 significantly stimulated tumor growth and chemoresistance in miR-382-overexpressing LS1034 cell Xenograft models." (PMID 29700213, 2019). "A recent study reported four circular isoforms of HIPK3, and showed that the predominant circHIPK3 is abundantly expressed in many tissues where it sponges nine different miRNAs, including the tumor suppressor miRNA miR-124." (PMID 29657280, 2017). "Here we show that knockdown of HIPK3 impairs tumour cell migration, induces formation of larger adhesions as well as inducing cellular force application and stability." (PMID 27531518, 2016). "In contrast, knockdown of KLF12 and HIPK3 respectively inhibited tumor growth and enhanced chemosensitivity in a miR-382-knockdown MNNG/HOS cell xenograft model." (PMID 25344865, 2014). "Our work led to the identification of a novel functional pathway controlled by miR-382 and its direct targets, KLF12 and HIPK3, that coordinate tumor growth and chemosensitivity, respectively, in OS." (PMID 25344865, 2014).